NLRP3 (NLR family pyrin domain containing 3)
Diseases named in the same sentence as NLRP3 in open-access papers (continued):
Sharing a sentence is not in itself a finding about the gene and the disease.
gout (continued). "In addition, we found that the decrease in PPAR-γ activity and production caused by MSU crystal stimulation is involved in the NLRP3 inflammasome activation that is part of the pathogenesis of gout." (PMID 37111279, 2023). "Although NLRP3 has been extensively linked to pathogenesis of gout, other NLRs may also contribute to this disease." (PMID 37598797, 2023). "The underlying mechanism of Prevotella in inducing gout inflammation might be by enhancing IL-1b production through activating NLRP3 inflammasome." (PMID 37344836, 2023). "To further learn the mechanisms underlying the interventional effect of EA on NLRP3 inflammasome, we examined whether EA might affect ROS production in inflamed ankle joints of gout model mice." (PMID 37464384, 2023). "Aberrant NLRP3 inflammasome activation is linked with the pathogenesis of multiple inflammatory diseases, such as cryopyrin­associated periodic syndromes, type 2 diabetes, non-alcoholic steatohepatitis, gout, and neurodegenerative diseases." (PMID 36741414, 2022). "NLRP3 inflammasome was considered as the main pathogenic factor in the pathogenesis of gout." (PMID 35462936, 2022). "In contrast, gout-associated uric acid crystals can activate NLRP3 inflammasome, resulting in GSDMD cleavage, IL-1β cytokine release, and the formation of membrane pores, suggesting that GSDMD may be actively involved in these diseases." (PMID 35774778, 2022). "MSU crystals could activate the NLRP3 inflammasome in macrophages and monocytes which is particularly associated with the initiation of gout flares." (PMID 35844867, 2022). "Therefore, NLRP3 inflammasome is demonstrated to link causal agents of gout and the disease pathogenesis." (PMID 36741414, 2022). "And what causes the activation of the NLRP3 inflammasome is partially transparent in gout." (PMID 36569836, 2022). "The dysregulation of the NLRP3 inflammasome pathway is associated with the development of many human diseases, such as atherosclerosis, metabolic syndromes, age-related macular degeneration, Alzheimer’s disease, and gout." (PMID 33440601, 2021). "Besides, an interesting experiment found that ethanol can upregulate the expression of P2X7 receptors to induce NLRP3 inflammasome activation, which partly explains why alcohol consumption predisposes to gout flares." (PMID 34925366, 2021). "NLRP3 has an important role in different pathologies, since the aberrant activation of this inflammasome is associated with several conditions, such as arthritis, gout, diabetes, Alzheimer’s disease or obesity." (PMID 33803783, 2021). "NLRP3 inflammasome activation is implicated in the etiology of gout." (PMID 33535473, 2021). "Dysfunction of the NLRP3 inflammasome is implicated in various inflammatory diseases, such as type 2 diabetes, neuron degenerate diseases and gout." (PMID 34603026, 2021). "The leucine-rich region located at the C-terminus of the NLRP3 molecule can recognize the endogenous danger signals caused by MSU, and then MSU combines with NLRP3 to promote the activation of NLRP3 inflammasomes and drive caspase-1 to process pro-IL-1β into mature IL-1β, which leads to gout flare." (PMID 33935726, 2021). "Numerous studies have shown that excessive activation of the NLRP3 inflammasome causes multiple autoinflammatory and autoimmune-associated metabolic disorders, including gout, type 2 diabetes, Alzheimer’s disease, atherosclerosis and cryopyrin-associated periodic syndromes (CAPS)." (PMID 34512673, 2021). "Therefore, in the present study, we investigated the mechanisms underlying the effects of gallic acid on the NLRP3 inflammasome and pyroptosis, as well as its effect on gouty arthritis in mice." (PMID 33365024, 2020).
gout (continued). "Only priming signal, however, is insufficient to activate the NLRP3 inflammasome unless the cells are activated by the activation signal, such as gout-causing monosodium urate (MSU) crystals, diabetes-causing saturated fatty acids, Alzheimer’s disease-causing amyloid-β and bacterial toxin nigericin." (PMID 31979265, 2020). "The NLRP3 inflammasome has been implicated in the pathology of many painful diseases and conditions such as bladder pain, neuropathic pain, rheumatoid arthritis, gout, migraine and many more." (PMID 32973552, 2020). "Gouty arthritis has been reported to be closely linked to NLRP3 inflammasome in joints." (PMID 32656909, 2020). "NLRP3 activation results in excessive inflammation, which is associated with a variety of inflammatory disorders, including type 1 diabetes, hyperinflammation following influenza infection, asthma and gout." (PMID 33614540, 2020). "Our study found the NLRP3 rs10754558 SNP and its haplotypes were associated with an increased susceptibility to gout; it may partly explain why less 10% of people with hyperuricemia develop gout finally." (PMID 29214547, 2018). "As de-sumoylation is critical for full NLRP3 activation, targeting SENPs may offer new opportunities for treating inflammatory diseases that are caused by aberrant activation of the NLRP3 inflammasome, such as type-II diabetes, gout, and Alzheimer’s disease." (PMID 30069026, 2018). "We investigated whether an orally administrable inhibitor of NLRP3 inflammasome was effective for alleviating the pathological symptoms of gouty arthritis and what was the underlying mechanism." (PMID 27934918, 2016). "Indeed, NLRP3 activation has been implicated in the development of many major diseases such as gout, type 2 diabetes, obesity-induced insulin resistance and depression." (PMID 27048470, 2016). "Excessive NLRP3 inflammasome activation underlies inflammatory diseases such as gout." (PMID 25655831, 2015). "Eleven functional variants were tested in eight genes involved in the MSU crystal-mediated activation of the NLRP3-inflammasome and production of mature IL-1β for association with gout in people of European and New Zealand (NZ) Polynesian (Māori and Pacific Island) ancestry." (PMID 26462562, 2015). "In a recent study, the intronic rs7512998 located in the NLRP3 gene showed a significant difference in the genetic frequency among the 17 tag SNPs from the NLRP3 gene that were investigated in association with the susceptibility to gouty arthritis in 480 primary gout and control patients." (PMID 25788762, 2015). "Targeting the inflammasome may therefore benefit joint pathologies allied with IL-1β production, such as OA, Muckle-Wells syndrome (an autoinflammatory disorder linked with mutations in NLRP3) and gout." (PMID 25175678, 2014). "Gouty arthritis is a metabolic disorder caused by purine metabolism dysregulation, characterized by monosodium urate crystal deposition in and around joints, triggering acute articular inflammation via NLRP3 inflammasome activation and IL-1β-mediated inflammatory cascades." (PMID 41583434, 2025). "Given that IL-1β is a major cytokine produced in response to MSU deposition and NLRP3 inflammasome activation is strongly linked to the development of gouty arthritis, targeting the NLRP3 inflammasome may be an effective therapeutic strategy for this condition." (PMID 39861092, 2024). "IGF1R might be associated with activation of the NLRP3 inflammasome in gout." (PMID 35813212, 2022). "Notably, these mice also showed impaired neutrophil influx after intraperitoneal MSU injection, demonstrating that the NLRP3 inflammasome is an important link between the well-established causal stimulation of gout and the subsequent pathological features of acute gout attacks." (PMID 35370689, 2022).
gout (continued). "On the other hand, over- or long-lasting activation of the NLRP3 inflammasome has been implicated in the development of a range of human acute or chronic inflammatory disorders, including inflammatory bowel disease, gout, atherosclerosis, diabetes, neurodegenerative disease, depression, and cancer." (PMID 36379253, 2022). "Over-activation of NLRP3 has been associated with many chronic inflammatory diseases such as Alzheimer’s disease, Parkinson’s disease, multiple sclerosis, metabolic disease and type 2 diabetes mellitus (T2D), atherosclerosis, gout, osteoarthritis, and rheumatoid arthritis." (PMID 32560261, 2020). "The aim of this present study was to determine whether single nucleotide polymorphisms (SNPs) in the NLRP3 gene are associated with susceptibility to gouty arthritis (GA) and whether these SNPs alter the expression of components of the NLRP3-IL1β signaling pathway." (PMID 29214547, 2018). "Thus, we concluded that NLRP3 gene haplotypes (including rs10754558) are likely associated with an increased susceptibility to gout and three NLRP3 SNPs might participate in development of gouty arthritis collectively." (PMID 29214547, 2018). "Given that the DAMPs are well-known direct activators of NLRP3 inflammasome and IL-1β production, further studies on variants responsible for the dysregulation of the NLRP3 inflammasome may provide an insight on the susceptibility of developing gout." (PMID 25788762, 2015). "These advances offer novel therapeutic strategies for NLRP3-driven pathologies including gouty arthritis, ischemia-reperfusion injury, neurodegenerative disorders, and metabolic syndromes." (PMID 42058220, 2026). "At the temporal level, acute gout flares are driven by innate immune activation of the NOD-like receptor pyrin domain-containing protein 3 (NLRP3)-interleukin-1β (IL-1β) inflammatory cascade." (PMID 41836392, 2026). "The upregulation of genes like”IL1B”and”CXCL2”in CD14+ monocytes further supports their involvement in the activation of the NLRP3 inflammasome, a critical pathway in gout pathogenesis." (PMID 40370447, 2025). "Several E3 ligases act as direct drivers of the disease, MDM2 is upregulated in gouty arthritis, where it mediates the ubiquitination and degradation of the protective nuclear receptor PPARγ, thereby unleashing NLRP3 activation." (PMID 41362701, 2025). "A new development in the approach to gout is that of NLRP3-targeted biologic agents, such as monoclonal therapies, to provide more accurate treatment by blocking specific pro-inflammatory cytokines." (PMID 39861750, 2025). "Background/Objectives: Gouty arthritis (GA) is a chronic inflammatory condition characterized by hyperuricemia and NLRP3 inflammasome activation, leading to joint damage and systemic inflammation." (PMID 40430581, 2025). "For example, Euodiae fructus is effective in alleviating asymptomatic HUA and gout by restoring UA metabolism and interrupting NLRP3 inflammasome activation, thereby inhibiting the production of proinflammatory cytokines in macrophages." (PMID 39935474, 2025). "This aligns with findings in other disorders where male sex is considered a risk factor, such as gout, aortic abdominal aneurysm and COVID19, in which the NLRP3 inflammasome was found to be overactivated in males and linked to worse disease outcomes." (PMID 39723571, 2025). "This calcium-dependent NLRP3 activation in macrophages, central to acute gouty arthritis, is mechanistically paralleled by similar processes in pancreatic β-cells (as discussed in Section 3.1.4) and contributes to the systemic chronic low-grade inflammation." (PMID 41301787, 2025). "As previously elaborated, calcium dysregulation is a key trigger for NLRP3 activation in both pancreatic β-cells (Section 3.1.4) and immune cells such as macrophages in gout (Section 4.1.2)." (PMID 41301787, 2025).
gout (continued). "In vivo and in vitro experiments demonstrated that miR-223-3p and miR-22-3p inhibit uric acid monosodium-induced gout inflammation by targeting NLRP3." (PMID 41311848, 2025). "Together, our findings suggest that auranofin alleviates MSU-induced inflammation by concurrently inhibiting NLRP3 inflammasome activation and IL-33-mediated neutrophil recruitment, supporting its potential as a dual-action therapeutic candidate for gout." (PMID 41090769, 2025). "Colchicine, traditionally used for gout and pericarditis, interferes with NLRP3 assembly by disrupting microtubule dynamics and cellular trafficking." (PMID 40648980, 2025). "In gout, monosodium urate crystals potently activate NLRP3, driving IL-1β release and acute inflammation." (PMID 40869653, 2025). "The concentration of HDAC6 (class II HDAC) in macrophages is upregulated in stimulation with MSU crystals, followed by the priming and activation of the NLRP3 inflammasome, promoting osteoclastogenesis in gout." (PMID 39935474, 2025). "Compounds such as cilantro protein have been found to inhibit TXNIP‐NLRP3 interaction, reducing ROS levels and cell pyroptosis, offering relief from NLRP3‐related conditions like gouty arthritis." (PMID 41298339, 2025). "OLT1177 proved to be reliable and potent for alleviating target joint pain in individuals with gout, a condition that depends on NLRP3 inflammasome activation, in an open-label phase 2A study." (PMID 40079000, 2025). "As a typical representative of the NOD-like receptor protein family, the accumulation of MSU crystals in the joints of gout patients can trigger the formation of NLRP3 inflammasomes." (PMID 40430440, 2025). "Throughout the pathogenesis of gout, disruptions in calcium signaling activate the NLRP3 inflammasome via multiple pathways." (PMID 41301787, 2025). "Meanwhile, the NLRP3 inflammasome pathway also was investigated in peritoneal cells, and similar results were obtained in the gout model." (PMID 39907694, 2025). "Activation of the NLRP3 inflammasome and production of bioactive interleukin-1β is central to the gout flare." (PMID 40874164, 2025). "The study revealed that the TET2 mutant CHIP is associated with increased gout risk in humans and identified CHIP as an amplifier of NLRP3-dependent inflammatory responses to MSU crystals in gout patients." (PMID 41311848, 2025). "Recent studies have revealed the significant role of NLRP3 inflammasomes invarious rheumatic diseases such as gouty arthritis." (PMID 41209134, 2025). "Colchicine has been demonstrated to inhibit the NLRP3 inflammasome and suppress caspase-1 activation in gout." (PMID 39792323, 2025). "In gouty arthritis, the intra—articular deposition of monosodium urate crystals activates the NLRP3 inflammasome, leading to the secretion of pro—inflammatory cytokines, including IL—1β, which mediate acute inflammatory responses." (PMID 40877572, 2025). "The abnormal expression and activity of NLRP3 inflammasome components are frequently observed in patients with gouty arthritis and animal models of the disease." (PMID 40430440, 2025). "The possible explanations for the significant increased cumulative incidence of asthma in patients with gout have been discussed in the previous section, including uric acid-related inflammation and the presence of NLRP3 inflammasome." (PMID 40299440, 2025). "For example, monosodium urate crystals in gout activate NF-κB and the NLRP3 inflammasome, leading to persistent inflammation and tissue injury." (PMID 41255516, 2025). "Another instance involves Simiao Powder, where compounds like quercetin target key inflammatory proteins such as IL-1β and TNF, modulating the NLRP3 inflammasome pathway to reduce gout-related inflammation." (PMID 41019543, 2025). "Previous research demonstrated that epicatechin alleviates MSU-induced acute gouty arthritis both in vitro and in vivo by inhibiting the NLRP3 inflammasome and the NF-κB signaling pathway." (PMID 41494226, 2025).
gout (continued). "Disulfiram (DSF), traditionally used to treat alcohol dependence, has recently emerged as a potent inhibitor of the NLRP3 inflammasome, offering a novel immunomodulatory strategy in gout management." (PMID 40430581, 2025). "The activation of the NLRP3 inflammasome in the inflammatory process mediated by MSU crystals has introduced new treatment options for gout." (PMID 39861750, 2025). "Dapansutrile (OLT1177), a β−sulfonyl nitrile compound with oral bioavailability, inhibits NLRP3 allosterically and has shown safety and anti−inflammatory effects in gout trials, with ongoing investigation in heart failure." (PMID 41488670, 2025). "Colchicine, an anti-inflammatory agent often used for conditions like gout, pericarditis, and Behcet's syndrome, works by blocking the activation of the NLRP3 inflammasome." (PMID 40360833, 2025). "Major inflammatory reactions in gout are associated with recruitment of innate immune cells, some of which respond to monosodium urate (MSU) crystals, triggering NLRP3 inflammasome activation." (PMID 40399065, 2025). "Given the rising interest in NLRP3 inhibitors and the need for effective gout therapies beyond urate-lowering agents, this study evaluates the synergistic potential of allopurinol and disulfiram in treating hyperuricemia and gouty arthritis." (PMID 40430581, 2025). "E3 ubiquitin ligases and related modifying enzymes are key regulators of the inflammatory cascade in gout, primarily by controlling the activation of the NLRP3 inflammasome and subsequent pyroptosis." (PMID 41362701, 2025). "CXCL1 orchestrates neutrophil-dominated inflammation in gout through feedforward loops with NLRP3 inflammasome activation." (PMID 40388724, 2025). "The initiation of acute gout is well-characterized by MSU crystal-induced NLRP3 inflammasome activation, leading to IL-1β release and NET-driven inflammation." (PMID 41190022, 2025). "Through this regulation, miR-23a-5p suppresses NLRP3 inflammasome activation, highlighting its potential as a therapeutic target for gout." (PMID 41578764, 2025). "This molecule has demonstrated efficacy in suppressing inflammation via inhibition of the NLRP3 inflammasome and modulation of the NF-κB signaling cascade, with therapeutic relevance in inflammatory pathologies such as gouty arthritis." (PMID 41011231, 2025). "NLRP3 inflammasome activation has emerged as a central mechanism in gout pathogenesis, presenting a therapeutic target beyond urate control." (PMID 40430581, 2025). "This has led to growing interest in inflammasome-targeted therapies, particularly NLRP3 inhibitors, which have emerged as promising alternatives for treating inflammation in gout beyond conventional NSAIDs and steroids." (PMID 40430581, 2025). "In gout, NF-κB and NLRP3 signaling interactions contribute significantly to tissue damage and inflammation." (PMID 40657393, 2025). "A central component in the pathogenesis of gout is the activation of the inflammasome known as the NOD-like receptor family pyrin domain-containing 3 (NLRP3)." (PMID 40722837, 2025). "Monosodium urate (MSU) crystals, which accumulate in the joints of patients with gout, serve as activators of the NLRP3 inflammasome." (PMID 40299440, 2025). "Our data suggested that Stefin B alleviated the gouty arthritis in mice by inducing the M2 polarization of macrophages and inhibiting the NLRP3 inflammasome." (PMID 38294507, 2024). "Activation of NLRP3 inflammasome by uric acid monosodium salt crystals and release of IL-1β play a major role in the initiation of gout attacks." (PMID 38376774, 2024). "The previous study also demonstrated that circHipk3 accelerates the production of CASP1 and NLRP3 in macrophages in gouty arthritis." (PMID 39601144, 2024). "In summary, ER exerts excellent anti-inflammation effects in a mouse model of HFD/PO-induced HUA and MSU-induced gouty arthritis by blocking NLRP3 inflammasome activation." (PMID 38708084, 2024).